IL6 (interleukin 6)
Diseases named in the same sentence as IL6 in open-access papers (continued):
Sharing a sentence is not in itself a finding about the gene and the disease.
tumor (continued). "Within the tumor microenvironment, studies have associated IL-6 production with CSCs." (PMID 34504657, 2021). "Furthermore, mice models have shown the immune-suppression role of IL-6 by inducing PD-L1 expression on tumor-associated macrophages, which are associated with immune-evasion." (PMID 34638361, 2021). "Moreover, the enhanced aerobic glycolysis in Epstein–Barr virus (EBV)-associated nasopharyngeal carcinoma prompts tumour cells to produce high amounts of IL-1β and IL-6, both of which are responsible for MDSC functions." (PMID 34685679, 2021). "Accumulation of IL-6 in the tumor microenvironment is associated with a functional defect in the DCs of cancer patients.This inhibitory effect is believed to be controlled by the IL-6-triggered activation of JAK2/STAT3 signaling in the DCs." (PMID 33568170, 2021). "In contrast, muscle loss was abolished by tumor cell depletion of IL-6." (PMID 33851955, 2021). "Moreover, IL-17 signaling in tumor cells and tumor-associated stromal cells can lead to IL-6 production and induce STAT3 activation." (PMID 34262562, 2021). "However, IL-6 serum levels are elevated in various tumor diseases and associated with aggressive tumor growth, impaired response to therapy, and poor prognosis." (PMID 34771524, 2021). "Interestingly, splenocyte supernatants obtained from an in vivo tumor model of disseminated PDA and repetitive intra-abdominal lavage via plasma-treated liquids showed decreased IL-6 levels associated with less tumor burden and increased survival." (PMID 34064000, 2021). "Notably, anti-IL-6 antibodies diminished PD-L1 expression, indicating that IL-6 plays a role in the PD-L1- induced immunosuppression associated with tumor expansion." (PMID 34899179, 2021). "Several other studies have suggested a role for such paracrine signaling events in Gemcitabine resistance, namely as blocking stromal protein synthesis via mTOR/4E-BP1 inhibition led to a reduction in tumor IL6, as well as the loss of drug-resistant phenotypes." (PMID 34336673, 2021). "Finally, IL-6 induces the development of immunosuppressive myeloid-derived suppressor cells (MDSCs) or tumor-associated macrophages (TAMs): their immunosuppressive functions occur through a STAT3-mediated mechanism." (PMID 34830209, 2021). "Second, miR-1246 in tumor EVs caused IL-6 induction through AR downregulation in ECs." (PMID 34226586, 2021). "Together, these findings demonstrate that blockade of IL6/8-JAK2 cascade could be a potential strategy to overcome BETi resistance caused by the tumor microenvironment." (PMID 34290255, 2021). "First, coculture with tumor cells inhibited the expression of M1-related genes encoding IL-6, TNF-α, and IL-1β and increased the expression of M2-related genes encoding CD163, Arg1, IL-10, TGF-β, and VEGFA, as well as expression of TNF-α and CD163 at protein level." (PMID 34093857, 2021). "The STAT-3 signaling pathway was also found to play a key role in meditating the effect of IL-6 on promoting tumor progression and treatment resistance by inhibiting cancer cell apoptosis and stimulating tumor-associated factors among various signaling pathways." (PMID 33582655, 2021). "Moreover, the observation that tumor-associated macrophages in irradiated tissue have enhanced secretion of pro-inflammatory cytokines IL-6, IL-12, TNF-α, and IFNγ further supports our results." (PMID 34298925, 2021). "However, a plethora of studies has implicated chronic inflammation in general and IL-6, specifically, in tumor initiation and progression." (PMID 33842333, 2021). "Tumor-associated macrophages (TAMs) expressing M2 (alternatively activated)-like phenotype imitate type II T-helper cells that express interleukin (IL)-4, IL-5, IL-6, IL-13, and IL-10 to suppress anti-tumor immune response." (PMID 34831357, 2021). "Recent studies have implicated that cytosolic transcription factor AhR is involved in Kyn associated tumor progression, and could transcriptionally induce the expression of IL-6." (PMID 34657635, 2021).
tumor (continued). "Additionally, it has been reported that wild-type flies fed a high-fat diet upregulate Upd/IL-6, a central inflammatory mediator implicated in many fly tumor phenotypes." (PMID 34831432, 2021). "An activated HSC can undergo senescence and become a senescence-associated secretory phenotype (SASP) that secretes tumor progression promoting cytokines (IL-6, IL-8), chemokines and proteases (matrix metalloproteinases, MMPs) which act to remodel the ECM and enhance inflammation." (PMID 32797354, 2021). "In this respect, an increase in IL-6 was associated with larger tumor size and liver metastases." (PMID 34476575, 2021). "Tumor-associated macrophages could produce IL-6, which would promote expansion of CSCs and tumorigenesis." (PMID 33391471, 2021). "The increase of IL6-/-;Eμ-myc in pre-tumor thymi may be due to altered homing signals associated with IL-6 deficiency." (PMID 33651821, 2021). "Whether caused by tumor-extrinsic and/or -intrinsic factors, chronically elevated circulating levels of IL-6, IL-1, and TNF-α would be expected to skew immune cells residing within skeletal muscle towards proinflammatory phenotypes." (PMID 33801684, 2021). "The prognosis of patients with HCC is heavily linked to liver function and tumor burden, and our findings show that IL6 could serve as a marker of the synthesis of both." (PMID 34080071, 2021). "Specifically, JAK-STAT signaling, triggered by the IL6/sIL-6Rα complex, activates extracellular signal-regulated protein kinase 1 and 2 and phosphoinositide 3-kinase downstream pathways that have been implicated in tumor cell growth." (PMID 34572592, 2021). "The stromal cells could also transform into tumor-associated stromal cells, which would further secrete many cytokines to promote tumorigenesis such as IL-6, IL-8, and vascular endothelial growth factor." (PMID 34381786, 2021). "Notably, IL-6 has also been shown to function as a contributor to the dynamic crosstalk between tumour cells and the carcinoma-associated fibroblasts (CAFs) in the TME." (PMID 34790130, 2021). "Regardless, IL-6 production from malignant cells can orchestrate cachexia, and this tumor characteristic could have diagnostic and therapeutic implications for PDAC." (PMID 33851955, 2021). "Furthermore, aberrant IL-6 expression is associated with aggressive tumor growth and resistance to therapies in many types of cancer." (PMID 33407508, 2021). "Consequently, loss of function and gain of function of IL-6 in tumor cells resulted in decreased and increased metastasis and corresponding MDP levels, respectively." (PMID 34140316, 2021). "Additionally, immune cell infiltrates of tumor-associated macrophages can produce IL-6 and TNFα in CRC." (PMID 34299049, 2021). "These Mφ, derived from monocytes recruited also by IL-6, are actually M2-like tumor-associated macrophages (TAM) which could express a series of cytokines including IL-6 to promote tumor progression." (PMID 33390844, 2021). "Studies have shown that IL-6 is associated with tumour progression in NSCLC35." (PMID 33658555, 2021). "To clarify the underlying mechanisms as well as the potential effects of IL-6 signaling on Bev anti-tumor activity, we examined these drugs in a co-culture system of the OCCC cell line RMG-1/GFP (emitting green fluorescence) and HUVEC pre-stained with Dil (emitting red fluorescence)." (PMID 33833265, 2021). "At the same time, the presence of myeloid-derived suppressor cells (MDSCs), IL-1 and IL-6 expression from cancer cells, M2-polarized tumor-associated macrophages (TAMs), and N2 tumor-associated neutrophils (TANs) are associated with attenuated response to ICI therapy." (PMID 33477635, 2021). "Further, IL-6 levels are associated with tumor growth and metastases." (PMID 33613850, 2021).
tumor (continued). "Notably, we observed that BCG-macrophage infusion attenuated tumor growth and was associated with an upregulation of the M1 macrophages associated genes including ifng, il6, and inos as well as with T cell activation and pro-inflammatory cytokine secretion." (PMID 34413847, 2021). "Additionally, IL-6 has been implicated in the regulation of matrix metalloproteinases (MMPs) involved in the processes of tumor invasion and metastasis." (PMID 34359685, 2021). "However, the potential role of IL-6 in tumor-associated Trp metabolism still remains incompletely understood." (PMID 34657635, 2021). "Tumor-associated macrophages coming from monocytes have a role in resistance to antivascular endothelial growth factor (VEGF) directed therapy by causing neutrophilia via interleukin-6 secretion." (PMID 33350295, 2021). "PNA-mediated release of MCP-1 and IL-6 causes autocrine/paracrine interactions with the endothelium and enhances the expression of a number of cell surface adhesion molecules which promote endothelial-tumour cell adhesion and endothelial tubule formation." (PMID 34223877, 2021). "Tumor cells obtained from inflamed liver tumors by introducing a prophlogistic IL-6-encoding DNA plasmid into β2SP+/− mice were more malignant than those obtained from tumors developed in IL-6-introduced wild-type mice." (PMID 33671768, 2021). "In addition, the susceptibility of tumor cells to the NK cytotoxic action was found to be reduced by CAA-derived IL-6 and leptin that activate the JAK/STAT3 signaling axis in tumor cells." (PMID 33917351, 2021). "miR-1246 in tumor EVs caused IL-6 induction through AR downregulation in ECs." (PMID 34226586, 2021). "Several publications have appeared in recent years documenting the increased expression of interleukin 8 (CXCL8, IL-8), interleukin 6 (IL-6), tumor necrosis factor (TNFα) in cancer cells, infiltrating neutrophils, endothelial cells and tumor-associated macrophages." (PMID 33266223, 2020). "Tumor-associated macrophages are a major source of IL-6 and TNFα in CRC." (PMID 32317968, 2020). "Notably, IL-6, a pro-inflammatory cytokine produced by different cell types, including immune cells, endothelial cells, cancer-associated fibroblasts, and tumor cells, is an important cytokine associated with chronic inflammation." (PMID 33167343, 2020). "These modifications of a Tfh-functional phenotype in FL could be in turn fostered by tumor cells through their increased expression of IL-6 and IL-7, both implicated in T cell homeostasis, memory T cell generation, and Tfh activation." (PMID 33028033, 2020). "Regarding targeted therapy for metastatic breast cancer, limited data suggest that CDK4/6 inhibitors may cause upregulation of IL-6 and IL-8 by tumor cells, although increases in systemic inflammation have not been documented to our knowledge." (PMID 33302472, 2020). "Physical activity was also linked with an upregulation of pathways associated with inflammation in the tumor (e.g., increased gene expression for IL-1-beta, IL-6, TNF-alpha) and immune function (e.g., increased gene expression of NKp46, NKG2D, CD68, CD209, CD8, CD74, FoxP3)." (PMID 33597950, 2020). "Similarly, increased expression of IL6 has been associated with tumor progression and metastasis but, at the same time, it is shown to augment adaptive immunity against tumor growth." (PMID 33123499, 2020). "Furthermore, high expressions of activated inflammasomes, IL-1β and IL-18, are also used as independent predictors of poor prognoses in ccRCC patients, while the tumor promoting cytokine, IL-6, has been implicated in the progression of RCC." (PMID 32714856, 2020). "We suggested that the measurement of IL-6 levels may be a useful method for identifying patients who are at a high risk of STSs and tumor-related death." (PMID 32138303, 2020).
tumor (continued). "Reducing tumor burden before T cell infusion may reduce the risk of cytokine release syndrome, and use of the IL-6–blocking antibody tocilizumab can be an effective treatment, should this syndrome arise." (PMID 33004686, 2020). "In addition, studies have demonstrated that the SASP from human senescent cells, particularly IL-6 and IL-8, induces an epithelial-to-mesenchyme transition, which is strongly associated with tumor progression and subsequent tissue invasion." (PMID 32528288, 2020). "Importantly, high concentrations of plasma IL-6 (>10 pg/mL) are associated with lower overall patient survival, and inhibition of IL-6 synthesis by tumor cells restores normal platelet numbers and improves disease control." (PMID 33042789, 2020). "Additionally, a number of tumor-derived cytokines are associated with an increased risk of all-cause mortality, perhaps most importantly IL-6." (PMID 32560494, 2020). "The IL6 pathway has been correlated with B regulatory cell (Breg) activation, which has been implicated in many immunological tolerance mechanisms such as organ transplantation, cancer, and self-stimulation of tumor cells." (PMID 33065980, 2020). "In Itgam−/− (αM deficient) mice, tumor growth and immunosuppressive cytokine mRNA levels are enhanced relative to wild type mice, whereas constitutive activation of the αM integrin by a point mutation knock in (C57BL/6 ITGA-M I332G) inhibits tumor growth, despite increased IL-6 mRNA levels." (PMID 32509583, 2020). "A more recent report closely linked to the current one showed that a mix of SCFA (butyrate, acetate, and propionate) was protective against AOM-induced CRC and was able to suppress key inflammatory cytokines such as IL-6 and inducing apoptosis in tumor-associated epithelial cells." (PMID 32526927, 2020). "Furthermore, tumor-associated macrophages (TAMs) participate in CRC metastasization through the TNF-α mediated secretion of IL6, which was also found to directly promote the accumulation of MDSCs in tumors." (PMID 32722560, 2020). "Tumor-associated macrophages (TAMs) are a major source of IL-6 and TNFα in CRC." (PMID 32317968, 2020). "In the same study, among patients with low AFP levels, increased IL-6 or IL-10 levels were significantly associated with the presence of HCC suggesting that these cytokines may be used as a tumor marker for patients with low AFP." (PMID 32284794, 2020). "IL-6/STAT3 is an important signaling pathway related to lncRNAs-caused tumor metastasis." (PMID 33520725, 2020). "We believe that the IL-6 autocrine loop in patients with STSs may be associated with tumor progression." (PMID 32138303, 2020). "Furthermore, a role for mTOR inhibitors in preventing and/or reversing tumour-associated cachexia through restoration of autophagy or reduction of IL-6 levels has been previously shown." (PMID 32577163, 2020). "IL-6 is a versatile cytokine responsible for regulating both immune and inflammatory responses and acts as an important modulator of activity of immune cells associated with tumor development." (PMID 33144870, 2020). "Interestingly, CSF-2 can induce M1-type polarization in macrophages, while CSF-2 and IL-6 derived from tumor-associated fibroblasts (CAFs) can synergistically induce the M2-type phenotype of TAMs." (PMID 33224886, 2020). "IL‐6 is a pleiotropic cytokine linked to pro‐inflammation, regeneration, and tumor development." (PMID 32810392, 2020). "Several studies showing that Cyr61 increases invasion and angiogenesis in several types of tumours led us to hypothesise that Cyr61 might be functionally linked to IL-6." (PMID 33228785, 2020). "Mechanistically, inhibition of PI3Kγ decreased TAM expression of genes associated with immune suppression and tumor angiogenesis (Arg1, Tgfb, Il1b, Il6, Vegfa), and upregulated expression of genes associated with anti-tumor immunity (Il12 and Ifng), suggesting TAM reprogramming." (PMID 33584701, 2020).
tumor (continued). "Tumor associated macrophages in the resting phase secrete immune-suppressive cytokine IL-10, while during activation by lipopolysaccharide (LPS), they secrete proinflammatory cytokines IL-1β, IL-6 and TNF." (PMID 32120819, 2020). "Moreover, IL-6 expression was also related to the tumor stage, while integrin β6 expression to M stage, indicating an association of IL-6 and integrin β6 expression with disease severity in the CRC patients." (PMID 32855767, 2020). "This accelerated cancer progression was accompanied by enhanced tumor-related angiogenesis and increased serum concentrations of several proinflammatory cytokines, including interleukin 6, and leptin, which suggested the potential association between MetS, inflammation, and cancer invasion." (PMID 32015762, 2020). "However, in the serum of CLL patients, high levels of IL-6 were associated with low levels of IL-1β, which seems to lead to the development of tumor cells." (PMID 33228048, 2020). "In conclusion, high plasma IL-5 at baseline could be a marker for ART-treated KS tumor regression, whereas increased pro-inflammatory cytokine IL-6, and the chemokine IP-10, associate with KS tumor progression." (PMID 32634155, 2020). "The results demonstrate, for the first time, a strong association of low muscle mass and high tumor IL-6 expression with mortality, a finding that could eventually be useful in treatment and prognostication in ccRCC." (PMID 32560494, 2020). "Notably, stromal stellate cells, which promote desmoplastic reaction in the tumor environment, also appear to upregulate proinflammatory cytokines such as IL-6 and recruit MDSCs and tumor-associated macrophages." (PMID 35582227, 2020). "In addition, myeloid-associated genes (COX2, IL8, IL1B) in the tumor and circulating cytokines (IL-8 and IL-6) were associated with resistance and shorter OS in urothelial bladder cancer patients treated with anti-PD-L1 (Atezolizumab or Durvalumab)." (PMID 32793228, 2020). "Then, we likely suggested that on 21st day, the tumour-bearing group (21 W) was subjected to more intense effects of the inflammatory process, higher interleukin IL-4 are associated with increased levels of IL-6, TNF and INF in the W group." (PMID 30975087, 2019). "Tumor-associated factors and IL-6 can increase the expression of Olfr29-ps1 in the MDSCs of mice." (PMID 31404149, 2019). "In addition to the production of IL-6 by muscles or osteoblasts, several types of cancer and associated stromal cells are involved in the production of this cytokine, which causes tumor growth and invasiveness in terminal cancer patients." (PMID 31010015, 2019). "Altogether, the preoperative serum IL-6 level may serve as a predictor for the tumor recurrence risk of HCC patients." (PMID 31781194, 2019). "Similarly, the baseline value of IL-6 was associated with tumour response, that is, IL-6 was higher in PD than PR patients." (PMID 31312030, 2019). "Interestingly, similar microenvironmental factors (e.g., IL-6 or tumor-associated factors) can induce the overexpression of lnc-C/EBPβ, lnc-CHOP, Olfr29-ps1, Pvt1, and RNCR3 in MDSCs." (PMID 31404149, 2019). "However, several reports showed that IL-6 is also playing a pro-tumoral role (by promoting the angiogenesis, the tumor progression and metastasis) and can be linked to a bad prognosis in patients." (PMID 31105699, 2019). "Increases in PD-L1 expression can occur on SCC cells as a result of mutations in tumor cell signaling pathways or exposure of tumor cells to inflammatory cytokines IL-1, IL-6, GM-CSF, IFNγ, TNFα, and VEGF and the gamma-chain cytokines IL-2, IL-7, IL-10, IL-15, and IL-21." (PMID 31554151, 2019). "In the TME, several tumor and tumor-associated cells produce and secrete factors that directly or indirectly prevent NK cell activation, including interleukin (IL)-6, IL-10, transforming growth factor-β (TGF-β), prostaglandin E2 (PGE2), and idoleamine 2,3-dioxygenase (IDO)." (PMID 31616440, 2019).